PLK1 (polo like kinase 1)
Diseases named in the same sentence as PLK1 in open-access papers (continued):
Sharing a sentence is not in itself a finding about the gene and the disease.
cancer (continued). "Antisense against Plk1 specifically inhibits cell proliferation of cancer cells in cell culture and in the nude-mouse tumour model, but did not inhibit growth and viability of primary cells." (PMID 12107831, 2002). "The Polo-like kinase 1 (Plk1) is a highly conserved mitotic serine/threonine kinase which is commonly overexpressed in cancer cell lines." (PMID 12107831, 2002). "Consequently, PLK1-mediatedinhibition of the SSP forces cancer cells to rely critically on exogenous serine uptake via the ASCT2 transporter." (PMID 41486146, 2026). "PLK1 inhibitor therapy has demonstrated efficacy in multiple cancer types." (PMID 41556056, 2026). "In addition, PLK1 inhibitors have been shown to selectively target cancer cells as radiation sensitizers and exert synergistic effects in combination immunotherapy." (PMID 40612941, 2025). "The high level of PLK1 expression associated with poorer overall survival (OS) outcome for cancer patients, whereas low expression indicates the OS is not significantly correlated, further suggesting that the cancer types are not at high risk." (PMID 41404416, 2025). "In summary, PLK1 may be an attractive target antigen for cancer immunotherapy, but is more likely to act as an accessory target rather than an independent immunotherapy antigen." (PMID 40612941, 2025). "This led to the overexpression of PLK1, which drives cancer progression." (PMID 40581078, 2025). "Inhibition of PLK1 activity by si-RNA or small molecule inhibitors demonstrates potent antitumor effects and synergizes with conventional chemotherapeutic agents in various pre-clinical models of cancer." (PMID 41458961, 2025). "PLK1 is an attractive target for cancer therapy because it is overexpressed in most human cancers." (PMID 41476654, 2025). "The SNPs of PLK1 were retrieved from 438 different cancer studies by querying 147,306 samples." (PMID 41404416, 2025). "However, owing in part to the large number of pathways in which PLK1 participates and the proteins it regulates, its role as a tumor suppressor in some types of cancer has recently been suggested, with experimental confirmation of this putative role." (PMID 40430225, 2025). "Several PLK1 inhibitors have been developed and evaluated for cancer treatment." (PMID 40852028, 2025). "BI6727(Volasertib), a PLK1 inhibitor, shows great promise as an anti-cancer drug." (PMID 40809688, 2025). "Additionally, the identification of specific-target drugs should focus on particular mutant forms of PLK1 to modulate the activity of cancer candidates, which aligns with the movement toward personalized medicinal approaches." (PMID 41404416, 2025). "This dual role of PLK1, coupled with its involvement in metabolic pathways like serine metabolism, highlights a critical gap in understanding how PLK1 orchestrates metabolic shifts in cancer." (PMID 40475404, 2025). "Combining PLK1 inhibition and immunotherapy may therefore be a promising way to achieve better antitumor effects as PLK1 inhibition not only selectively kills cancer cells but also upregulated PD-L1 expression in the remaining cells." (PMID 40615690, 2025). "Plk1 is involved in inositol-requiring protein 1a (IRE1a, a cell stress sensor)-mediated induction of apoptosis and inhibition of proliferation in response to ER stress in cancer cells." (PMID 40166466, 2025). "Numerous publications reveal PLK1’s role in promoting cancer development, progression, and resistance to chemotherapy agents, such as doxorubicin, gemcitabine, and taxol, in multiple types of cancers." (PMID 41284701, 2025). "In addition, there is evidence for a correlation between PLK1 and cancer chemotherapy drug resistance, including paclitaxel and gemcitabine." (PMID 40665355, 2025). "We found that the expression of a subset of PLK1-SDL hits was positively correlated with PLK1 levels across several cancer types, suggesting that these hits may represent specific genetic dependencies of PLK1-overexpressing cells." (PMID 40347943, 2025).
cancer (continued). "As a result, PLK1-overexpressing cancer cells are heavily reliant on high rates of ATP production." (PMID 40347943, 2025). "The data presented here show that, in addition to FOXM1, targeting AURKB and PLK1 may curb the increased cell proliferative activity of cancer cells." (PMID 40149290, 2025). "Future studies that explore the role of these proteins may also point toward new therapeutic avenues for the treatment of PLK1-overexpressing cancers." (PMID 40347943, 2025). "We hypothesized that the first and second circuits, centered on mitotic checkpoint regulation, microtubules, and kinetochore dynamics, are the main pathways by which plk1 contributes to the genomic instability events observed in cancer." (PMID 40430225, 2025). "Thus, genomic instability has emerged as an important mechanism for explaining the tumor suppressor/oncogenic role of plk1 in cancer." (PMID 40430225, 2025). "Further investigation into PLK1’s impact on cancer metabolism could lead to the development of novel precision medicine strategies to combat this aggressive disease." (PMID 40475404, 2025). "Transcriptomic profiles provide evidence that changes in plk1 expression levels are accompanied by similar changes in the genes comprising the first and second circuits and, to some extent, the third circuit, across at least 16 different cancer types." (PMID 40430225, 2025). "Targeting the SSP, serine uptake, or downstream lipid biosynthetic pathways may offer promising therapeutic avenues in PLK1-high advanced cancers." (PMID 40475404, 2025). "According to these results, the first circuit by which PLK1 may participate in a genomic instability event in cancer is through deregulation of the chromosomal passenger complex [CPC] and the Aurora kinase B [AURKB] regulatory pathway." (PMID 40430225, 2025). "In recent years, it has been found that PLK1 may be a universal tumor antigen recognized by cytotoxic T lymphocytes for cancer immunotherapy." (PMID 40612941, 2025). "Analysis of drug sensitivities between SCLC-Y and other subtypes of SCLC cell lines using the Cancer Therapeutics Response Portal database revealed specific drug candidates, including PLK1 inhibitors, that showed potent and highly selective activity in SCLC-Y cell lines." (PMID 39941812, 2025). "Furthermore, PLK1 represents a promising target antigen for cancer immunotherapy, with potential applications in optimizing cancer vaccines." (PMID 40612941, 2025). "Indeed, we observed cleaved PARP in all innately PLK1-high cancer cells treated with higher doses of the compound." (PMID 40347943, 2025). "In general, PLK1 is viewed as an oncogene and a possible target for cancer therapies." (PMID 40486867, 2025). "All these findings highlighted the importance of PLK1 expression in different cancers and suggested it could be a potential target for cancer treatment." (PMID 41404416, 2025). "In parallel, PLK1, a key regulator of mitotic entry and spindle assembly, has emerged as a critical player in cancer progression." (PMID 40475404, 2025). "Importantly, the therapeutic efficacy of small-molecular inhibitors targeting PLK1 is an ongoing area of clinical evaluation for the treatment of a range of cancers." (PMID 40111122, 2025). "Notably, PLK1 exhibited overexpression in diverse cancer types and is related to the tumorigenesis and progression in multiple cancers." (PMID 40845073, 2025). "Interestingly, PLK1’s role is context-dependent, as it can inhibit progression in some cancers, adding complexity to its function in tumor biology." (PMID 40475404, 2025). "Overview of PLK1 substrates and functions related to cancer." (PMID 40612941, 2025). "PLK1 inhibition can selectively kill cancer cells that are addicted to PLK1 overexpression." (PMID 40379873, 2025).
cancer (continued). "PLK1 drives cellular proliferation, is overexpressed in a wide range of tumors, and is associated with poor clinical outcomes, making this kinase an attractive candidate for targeted cancer therapeutics and prompting the clinical development of multiple PLK1 inhibitors." (PMID 40111122, 2025). "Given its critical role in cell cycle regulation, the inhibition of PLK1 activity has been shown to significantly inhibit the proliferation of a wide range of cancer cell lines, thus emphasizing its considerable promise as a therapeutic target for cancer therapy." (PMID 40801655, 2025). "A canonical pathway analysis revealed that the AR/AR-V7-independent HSF1–DBC1 cotarget genes were highly enriched in pathways associated with cancer metastasis, including matrisome-related (NABA gene sets), Fanconi, PLK1 and Wnt signaling pathways, compared with HSF1–DBC1-AR/AR-V7 common targets." (PMID 41028522, 2025). "Importantly, this study is the first attempt to propose a nano‐inhibitor of PLK1, thus leading to a remarkably promising direction for future cancer chemotherapy." (PMID 41476654, 2025). "PLK1 has been found to play a significant immunomodulatory role in almost all types of cancer." (PMID 40612941, 2025). "PLK1 and Aurora A kinase coinhibition suppress mitosis in cancer cells." (PMID 39949984, 2025). "Targeting Plk1 by onvansertib has been shown to have anti-tumor activity in pre-clinical models of multiple cancers and is currently being evaluated in phase 1 and 2 clinical trials in cancer patients." (PMID 40166466, 2025). "One of these kinases, polo-like kinase 1 (PLK1), has been linked to cancer development in humans." (PMID 41329781, 2025). "Currently, PLK1 inhibitors are being evaluated in clinical trials across a range of cancers." (PMID 40093809, 2025). "B4 disrupted the PLK1-PRC1 interaction and led to PLK1 KD inhibition-like mitotic catastrophes, suggesting that the compound could be used as a selective PLK1 inhibitor for cancer therapy." (PMID 40355412, 2025). "This study provides compelling evidence for IGF2BP2 as a target in PLK1-overexpressing cancers." (PMID 40347943, 2025). "Recently, the PLK1 has emerged as a key oncogenic target in cancer research." (PMID 41404416, 2025). "Taken together, these studies suggest that IGF2BP2 inhibitors have high therapeutic potential and that with further refinement the application of these compounds would allow us to effectively reduce PLK1 protein levels and ultimately suppress PLK1-overexpressing cancer cells and tumors." (PMID 40347943, 2025). "The potential of PLK1 inhibitors as cancer therapeutics has been extensively investigated." (PMID 40612941, 2025). "Moreover, PLK1 can regulate the expression of immune checkpoint-related proteins, thereby playing a synergistic role in cancer therapy." (PMID 40612941, 2025). "Therefore, investigating the regulation of PLK1 expression/activity in cancers is of vital importance." (PMID 41022752, 2025). "Based on the three PLK1 protein-interaction circuits reported in this study, the model explains how dysregulation, either with increase or decreases in plk1 levels, can generate genomic instability events in different carcinomas, emerging as a comprehensive tool for cancer research." (PMID 40430225, 2025). "PLK1 is a potent oncogene and, therefore, an ideal drug target for anti-cancer therapy." (PMID 37992487, 2024). "Hence, we suggest that BAL0891 represents a first-in-class TTK/PLK1 inhibitor for the treatment of cancer patients." (PMID 39184047, 2024). "Since the activation of RhoA is required for cancer cell migration and PLK1 enhances RhoA activity through the interaction with RhoGDI1, we investigated whether PLK1 could affect the migration and invasion of cancer cells." (PMID 38355643, 2024).
cancer (continued). "PLK1 is a key mitotic protein kinase that plays a critical role in cell division and serves as a major regulator of cellular proliferation, making it an attractive therapeutic target for cancer treatment." (PMID 39451218, 2024). "Therefore, PLK-1 acts as a master regulator of cell division and vulnerability, especially in cancer cells, leading to an ideal target to interrupt the dysregulated proliferative rates in malignancies." (PMID 39684470, 2024). "Here, we report a novel mechanism of PLK1 in cancer promotion." (PMID 38885192, 2024). "Several mechanisms of how PLK1 can drive the EMT process in different cancers." (PMID 39451218, 2024). "Due to its oncogenic functions, PLK1 has emerged as a promising target for cancer therapy." (PMID 38780513, 2024). "PLK1 has emerged as a pivotal regulator of the cancer stem cell (CSC) phenotype." (PMID 39451218, 2024). "Many studies have showed that inhibition of PLK1 could lead to death of cancer cells by interfering with multiple stages of mitosis." (PMID 38783288, 2024). "PLK1 exerts a pivotal role in sustaining the characteristics of cancer stemness." (PMID 39451218, 2024). "Increased expression of PLK1 is observed in malignant cells, leading to defects in mitosis and cytokinesis as well as increased chromosomal instability, which is a common feature of many cancers." (PMID 38393054, 2024). "Transwell migration and invasion assays revealed that treatment with BI 6727 significantly reduced the motility and invasiveness of HeLa cells compared with DMSO-treated HeLa cells, suggesting that PLK1 activity is critical for cancer cell migration and invasion." (PMID 38355643, 2024). "PLK1 regulates many aspects of the cell cycle, and its dysregulation is a common feature of cancer." (PMID 38612439, 2024). "Consequently, PLK-1 acts as an oncogene in multiple cancers, with its overexpression being correlated with poor prognosis and its knockdown leading to cancer cell death." (PMID 38540116, 2024). "Despite several studies indicating a correlation between PLK1 expression and the aggressiveness of cancers, including CRC, the specific role of PLK1 in the metastatic progression of CRC and the mechanisms driving PLK1-induced EMT remain under active investigation." (PMID 39451218, 2024). "On the other hand, overexpression of some specific enzymes, e.g., cyclin-dependent kinases (CDK4, CDK6, and CDK2), polo-like kinase 1 (PLK1), and aurora kinases (aurora A and aurora B), can induce or contribute to tumorigenesis, which drives cancer progression." (PMID 39204341, 2024). "Additionally, previous studies have demonstrated that PRC1 is associated with other key factors, including Wnt/β-catenin, polo-like kinase 1 (PLK1), and the p21/p27 family in various cancers." (PMID 39409930, 2024). "The malfunction or overexpression of PLK1 can contribute to cancer development and progression." (PMID 39456780, 2024). "Our data suggest that inhibiting the PLK1/RhoGDI1 interaction using a synthetic peptide derived from RhoGDI1 may be a potential therapeutic approach for cancer treatment." (PMID 38355643, 2024). "Consistent with previous research, our investigation showed that patients younger than 50 years have a higher prevalence of high-grade carcinomas; however, a statistically significant association between PLK-1 expression and tumor grade was not established." (PMID 39857637, 2024). "Indeed, more than 10 PLK1-specific inhibitors are commercially available, and some of them have been assessed in clinical trials for different types of cancers." (PMID 37447165, 2023). "Together, these results suggested that PLK1 is important for KRASG12C-mutant cancer progression." (PMID 38104151, 2023). "Recently, Plk1 has been reported to regulate autophagy in various cancer cells." (PMID 37640723, 2023).
cancer (continued). "In addition, we review the prognostic and clinical significance of these proteins in human cancers and, more importantly, the different approaches that have been used to disrupt PLK1 and FOX TF-mediated signaling networks." (PMID 37174744, 2023). "Unraveling the mechanisms by which PLK1 regulates necroptosis and its implications for tumor development, treatment response, and the immune microenvironment holds promise in paving the way for novel therapeutic strategies targeting PLK1 in cancer." (PMID 37744268, 2023). "In addition, a significant reduction in CDK2 mRNA expression was observed across all tested pan-cancer cell lines upon the pharmacological co-inhibition of PLK1 and ACLY." (PMID 37958642, 2023). "PLK1 is aberrantly expressed in various cancers and related to patient prognosis." (PMID 38186570, 2023). "ASO-based PLK1 gene engineering has been widely explored as an attractive method in cancer therapy." (PMID 37580346, 2023). "Therefore, further investigations are warranted to comprehensively elucidate the intricate relationship between PLK1 and necroptosis, particularly within the context of cancer." (PMID 37744268, 2023). "However, numerous studies have demonstrated that PLK1 was overexpressed in a variety of human tumors, and its high expression level often correlates with poor prognosis in cancer patients, suggesting that PLK1 is critical for tumorigenesis." (PMID 36805592, 2023). "Moreover, pan-cancer patients with upregulated PLK1, CEP55, FANCI, NEK2, and PTTG1 exhibited a poorer overall survival rate and disease-free survival." (PMID 37274251, 2023). "Unsurprisingly, PLK1 is expressed in various types of malignancy and, despite some of them being described as a tumor suppressor, its overexpression was widely correlated to poor prognosis in cancer, including BC." (PMID 37447165, 2023). "In principle, if cells become dependent on the functions of particular proteins when PLK1 activity is decreased, inhibiting these proteins and PLK1 simultaneously might more effectively target cancer cells." (PMID 37639469, 2023). "Because of its wide functions, PLK1 is an oncogene frequently dysregulated in many cancers." (PMID 37988371, 2023). "Evidence has indicated that some PC-related protein dysfunction could promote cancer development, such as PLK1, PLK4, AURKA, and so on." (PMID 37101292, 2023). "PLK1 has been the subject of most research as a potential target for cancer treatment." (PMID 36597205, 2023). "Moreover, while drugs have been developed against PLK1 for cancer treatment, these compounds alone are largely ineffective." (PMID 37639469, 2023). "Furthermore, we discuss the therapeutic potential of targeting PLK1-regulated FOX TFs in human cancers." (PMID 37174744, 2023). "The results suggest that both UBE2C and PLK1 may promote the occurrence and development of pan-cancer by separately influencing the cell cycle." (PMID 37958642, 2023). "The targeting of ACLY and PLK1, or alternatively, the simultaneous targeting of other dysregulated metabolic pathways while starting from cell-cycle-related proteins, presents novel prospects for cancer treatment." (PMID 37958642, 2023). "CDC20 and PLK1 are both located at chromosomal region 9p, which is often amplified in cancer." (PMID 37509260, 2023). "Consequently, PLK1 inhibitors have been developed and are currently under examination as potential anti-cancer agents." (PMID 38234395, 2023). "PLK1 was significantly increased in 13 types of cancer between different pathological stages." (PMID 37958642, 2023). "Consistent with the reports of previous studies, our results indicated that PLK1 inhibition could induce extensive apoptosis and DNA damage of cancer cells in vivo and in vitro." (PMID 36805592, 2023).